GAS8-AS1 (GAS8 antisense RNA 1)
Synonyms: C16orf3
Gene: Long non-coding RNA gene on chromosome 16 (90,028,908 to 90,029,901, reverse strand). Ensembl gene ENSG00000221819.
Diseases named in the same sentence as GAS8-AS1 in open-access papers:
GAS8-AS1 is named in the same sentence as 4 diseases in open-access papers, as found by Europe PMC text mining. Sharing a sentence is not in itself a finding about the gene and the disease. The quoted sentences say what the papers report.
hepatocellular carcinoma (1 paper, 2021). A malignant tumor that arises from hepatocytes. "In hepatocellular carcinoma (HCC), GAS8 antisense RNA 1 (GAS8-AS1) recruited H3K4 methyltransferase MLL1 to the promoter of GAS8 and enhanced the H3K4 m3 level, thereby upregulating the expression level of GAS8." (PMID 33428595, 2021).
papillary thyroid carcinoma (1 paper, 2019). "The aim of the present study was to investigate the potential role of GAS8 antisense RNA 1 (GAS8-AS1) in papillary thyroid carcinoma (PTC)." (PMID 30429236, 2019).
tumor (2 papers, 2019 to 2020). "GAS8 antisense RNA 1 (GAS8-AS1) is located in the second intron of GAS8 and transcribes a 994 nt ncRNA in the opposite orientation of GAS8, which is reported to be a novel tumor suppressor that affects tumor cell proliferation in PTC." (PMID 32596158, 2020).
GAS8-AS1 also shares sentences with these, for which no sentence is quoted: Thyroid Carcinoma (1 paper).